MCM10 (minichromosome maintenance 10 replication initiation factor)
Description:
Acts as a replication initiation factor that brings together the MCM2-7 helicase and the DNA polymerase alpha/primase complex in order to initiate DNA replication. Additionally, plays a role in preventing DNA damage during replication. Key effector of the RBBP6 and ZBTB38-mediated regulation of DNA-replication and common fragile sites stability; acts as a direct target of transcriptional repression by ZBTB38.
Synonyms: PRO2249; CNA43; DNA43; IMD80
Tractability: PROTAC: UniProt records ubiquitination sites on it; ubiquitination databases record sites on it.
Gene: Protein-coding gene on chromosome 10 (13,161,554 to 13,211,110, forward strand). Ensembl gene ENSG00000065328.
Subcellular location: Nucleus
Subcellular location (Human Protein Atlas): Nucleoli; Nucleoplasm
Pathways (Reactome):
Cell Cycle: Activation of ATR in response to replication stress
DNA Replication: Activation of the pre-replicative complex
Gene Ontology:
Molecular function: identical protein binding; protein binding; DNA replication origin binding; single-stranded DNA binding; double-stranded DNA binding; enzyme binding
Biological process: DNA damage response; DNA replication initiation; DNA replication
Cellular component: nucleolus; nucleoplasm; nucleus; nuclear replication fork
Genetic constraint (gnomAD): Loss-of-function variants: 71 observed, 92.18 expected, observed/expected ratio (o/e) 0.77, 90% interval 0.63 to 0.94. The upper end of that interval is the gene's LOEUF score, 0.94, which puts it in group 3 of 6, group 1 being the genes least tolerant of losing a copy. Missense variants: 1,006 observed, 1,036.3 expected, observed/expected ratio (o/e) 0.97, 90% interval 0.92 to 1.02. Synonymous variants: 359 observed, 384.6 expected, observed/expected ratio (o/e) 0.93, 90% interval 0.86 to 1.02.
Gene-disease validity (ClinGen):
ClinGen rates the evidence that MCM10 causes each of these diseases.
immunodeficiency 80 with or without congenital cardiomyopathy (autosomal recessive): Moderate. An autosomal recessive immunologic disorder with variable manifestations.
Homologues: Orthologues: chimpanzee MCM10 (99% identical), macaque MCM10 (96% identical), pig MCM10 (84% identical), rat Mcm10 (78% identical), rabbit MCM10 (77% identical), guinea pig MCM10 (77% identical), mouse Mcm10 (76% identical), tropical clawed frog mcm10 (57% identical), zebrafish mcm10 (47% identical), Drosophila melanogaster Mcm10 (26% identical), Caenorhabditis elegans mcm-10 (21% identical).
Diseases named in the same sentence as MCM10 in open-access papers:
MCM10 is named in the same sentence as 63 diseases in open-access papers, as found by Europe PMC text mining. Sharing a sentence is not in itself a finding about the gene and the disease. The quoted sentences say what the papers report.
breast carcinoma (20 papers, 2018 to 2025). "In another study, Yang and colleagues introduced MCM10 as a potential diagnostic tool and a promising target for breast carcinoma." (PMID 37746664, 2023). "Survival analysis revealed that high MCM10 expression was associated with poor prognosis in breast cancer." (PMID 36233194, 2022). "Here, using a breast cancer model, we observe a significant association of MCM10 with the degree of clinical aggressiveness in breast cancer patients." (PMID 35813483, 2022). "Most importantly, using breast cancer cohorts with available treatment information, we also demonstrated that a high level of MCM10 is associated with a better response to conventional treatment." (PMID 30135378, 2018). "A high expression level of MCM10 in tumor specimens was associated with a shorter survival time in all six breast cancer patient datasets tested (n = 1283)." (PMID 30135378, 2018). "To validate our hypothesis and discover the underlying mechanism, we observed expression levels of MCM10 in breast cancer patients having a different degree of aggressiveness." (PMID 35813483, 2022). "In this study, we hypothesized that expression levels of MCM10 are associated with the degree of aggressiveness in clinical breast cancer patients, and increased MCM10 could enhance the cancer-like characteristics in normal cells." (PMID 35813483, 2022). "In the present study, we have demonstrated that (i) MCM10 was highly expressed in human breast cancer specimens compared to normal breast epithelium, in vitro and (ii) a high MCM10 expression level was associated with a significantly shorter time of breast cancer patient survival." (PMID 30135378, 2018). "In total, six independent breast cancer patient cohorts with 1283 individual patients were included in the present study for the survival analysis; the robust results from these six independent cohorts suggest that the association between MCM10 expression and patient survival was consistent." (PMID 30135378, 2018). "Just like other MCMs, the variation of MCM10 gene has been found in many cancers, such as breast cancer, ovarian cancer and gastric cancer." (PMID 37246638, 2023). "This unbiased approach allowed us to identify a panel of five biomarkers, DNMT3B, EXO1, MCM10, CENPF and CENPE, that are robustly and significantly associated with disease-free survival prognosis in breast cancer." (PMID 37592220, 2023). "Yang and Wang8 denoted that MCM10 drives breast cancer cell malignant behaviors via Wnt/β-catenin signaling." (PMID 37860833, 2023). "MCM10 was also suggested as a potential prognostic biomarker in breast cancer and in hepatocellular carcinoma." (PMID 37592220, 2023). "A previous study showed that MCM10 facilitates the migration potential of breast cancer cells via Wnt/β‐catenin signalling and is positively correlated with a poor prognosis." (PMID 36347834, 2022). "In the present study, using breast cancer models we explored the relevance of MCM10 expression levels with breast cancer aggressiveness and validated our results in clinical Breast cancer (BC) patient samples." (PMID 35813483, 2022). "Overall, the findings of this study revealed a novel mechanism by which MCM10 promotes genomic instability and breast cancer progression, and effectively differentiates the active degree of breast cancer aggressiveness." (PMID 35813483, 2022). "MCM10 OE was able to increase RPA2 compared to controls in breast cancer patient biopsy and in MCF10A OE cells, which further induced high expression of downstream proteins ATR and CHEK1, supporting the possibility of increased ssDNA in MCM10 OE cells." (PMID 35813483, 2022). "Altogether these observations indicated the role of MCM10 in inducing DNA replication catastrophe and dictating the aggressiveness of breast cancer." (PMID 35813483, 2022). "MCM10 was reported to play an important role in several tumors including breast cancer and urothelial carcinoma." (PMID 34239894, 2021).
breast carcinoma (continued). "We found that MCM10 is highly expressed in a variety of cancers in addition to lung cancer, including colorectal cancer and breast cancer." (PMID 33604163, 2021). "MCM10 is also involved in the formation and development of multiple tumors, including glioma, prostate cancer, urothelial cancer, neuroblastoma, and breast cancer." (PMID 34490114, 2021). "In a recent study, MCM10 induced migration and invasion of breast cancer via the Wnt/β-catenin pathway." (PMID 33013420, 2020). "The diagnostic values of the individual MCM subunits were identified in various cancers including MCM2 in gastric cardiac cancer and salivary gland tumor, MCM5 in esophageal cancer, MCM7 in meningiomas, and MCM10 in breast cancer." (PMID 32089988, 2020). "Knockdown of MCM10 in ER positive breast cancer cells also reduced cell proliferation rate and cancer migration." (PMID 30135378, 2018). "Our data demonstrated that MCM10 plays an important in breast cancer progression and is a potential prognostic biomarker as well as a therapeutic target for breast cancer patients." (PMID 30135378, 2018). "Consistently, observed in three independent datasets, breast cancer patients who achieved pCR by neoadjuvant chemotherapy had a significantly higher MCM10 expression level." (PMID 30135378, 2018). "Our results suggest that MCM10 plays an important role in breast cancer progression and is a potential prognostic/predictive biomarker and therapeutic target for breast cancer patients." (PMID 30135378, 2018). "The MCF7 breast cancer cell line, after MCM10 expression knockdown, showed significantly decreased tumorigenic properties such as cell proliferation, migration, and anchorage independent growth." (PMID 30135378, 2018). "In the present study, we focused on understanding the importance of MCM10 and its regulation during breast cancer progression by using publicly available breast cancer patient cohorts, in vitro cell line experiments and in vivo mouse models." (PMID 30135378, 2018). "Four out of the six independent breast cancer patient datasets have available information on tumor grading; therefore, we compared the expression level of MCM10 mRNA between tumors with different grades in these four datasets." (PMID 30135378, 2018). "Reduction of cancer cell properties after MCM10 knockdown in ER positive breast cancer cells was in parallel to three independent ER-positive breast cancer patient cohorts with less expression of MCM10 and longer survival time." (PMID 30135378, 2018). "It was shown that the expression level of MCM10 was higher in breast cancer cell lines." (PMID 39195643, 2024). "Thus, according to research, MCM10 inhibiting molecules can be employed to target breast cancer CSCs as well as tumors." (PMID 36499614, 2022). "Notably, MCM10 overexpression was observed in breast cancer patients, and knockdown of MCM10 dramatically reduced tumor cell growth in the mouse model of breast cancer." (PMID 36233194, 2022). "Thus, MCM10 has the potential to be a clinically useful biomarker as well as a therapeutic target for future breast cancer treatment." (PMID 35813483, 2022). "In conclusion, the current study showed that CCNE2, CDCA5, RAD51, TCF19, KNTC1, MCM10, and NEIL3 might contribute to EPT-related tumorigenesis in breast cancer, with CCNE2 might be a sensitive risk indicator of breast cancer risk in women using MHT." (PMID 36233194, 2022). "Besides, results of western blot analysis showed that β-catenin and cyclin D1 were downregulated in MCM10 knockdown cells, suggesting that downregulated MCM10 suppressed metastasis in breast cancer via the Wnt/β-catenin pathway." (PMID 32089988, 2020). "Gene Expression Omnibus (GEO), The Cancer Genome Atlas (TCGA), and other online cancer microarray databases combined with the Kaplan-Meier Plotter have been used to identify the unfavorable roles of highly expressed MCM10 in breast cancer and hepatocellular carcinoma." (PMID 32089988, 2020).
breast carcinoma (continued). "In addition, 5 hub genes, CCNB2, FBXO5, KIF4A, MCM10, and TPX2 were identified and validated to be associated with the progression and worse prognosis of breast cancer." (PMID 30254986, 2018). "To investigate how MCM10 may contribute to breast cancer progression, we knocked down MCM10 expression in MCF 7 cells and then tested the cellular properties, including cell proliferation and migration." (PMID 30135378, 2018). "Similarly, in in vitro studies, the expression level of MCM10 in breast cancer cell lines is significantly higher compared to paired normal breast epithelium cells." (PMID 30135378, 2018). "Here, we studied the role of MCM10, a novel licensing factor, in breast cancer progression." (PMID 30135378, 2018). "These consistent results obtained in three independent breast cancer datasets suggest that tumors with higher MCM10 expression may be more prompt to respond to neoadjuvant treatment." (PMID 30135378, 2018). "We further studied the expression of MCM10 in breast cancer cell lines." (PMID 30135378, 2018). "Since the observations were consistent among all six independent breast cancer patient datasets, our results strongly suggest that MCM10 alone could be a prognostic marker for breast cancer patients." (PMID 30135378, 2018). "Similarly, protein expression of MCM10 was significantly higher in tumor specimens compared to its normal breast epithelium counterparts, confirming our observation using microarray data in six independent breast cancer patient cohorts." (PMID 30135378, 2018). "Similarly, MCM10 knockdown MCF-7 cells also had a significantly lower migration and soft agar colony formation potential, suggesting that reducing the expression of MCM10 may reduce the aggressiveness of breast cancer cells." (PMID 30135378, 2018). "In addition, these MCM10 knockdown cells had a slower growth rate compared to control cells in vivo, suggesting that MCM10 plays an important role in cancer-related properties in breast cancer cells." (PMID 30135378, 2018). "In this study, data from breast cancer, cervical cancer, uterine sarcoma and UCEC in The Cancer Genome Atlas (TCGA) database were used to screen novel biomarkers, and MCM10 was identified to be an effective indicator to predict UCEC prognosis." (PMID 37246638, 2023). "In our study, we report potential links to MCM10 expression levels and breast cancer aggressiveness as well as a novel mechanism by which MCM10 can accumulate DNA damage without inducing stress signals." (PMID 35813483, 2022). "In conclusion, the overexpression of AURKB, GINS2, MCM10, UHRF1, POLE2, SPC24, and E2F2 in HER2-positive breast cancer patients with ALR showed that these hub genes could be potential prognostic biomarkers in such patients." (PMID 33013420, 2020). "Similar to the other six independent breast cancer datasets, in GSE22226, even with standard neoadjuvant treatment, patients with a high level expression of MCM10 had a significantly shorter survival time compared to those with a low level expression of MCM10 (p = 0.013)." (PMID 30135378, 2018). "We analyzed the expression patterns of MCM10 in relation to BC in patient cohorts by acquiring microarray gene expression data from the GENT2 database, in ex-vivo patients specimens having a different degree of BC malignancy and, in less aggressive and highly aggressive breast cancer cell lines." (PMID 35813483, 2022). "However, to our best knowledge, no report has extensively investigated the significance of MCM10 in breast cancer." (PMID 30135378, 2018). "These analyses revealed five genes, DNMT3B, EXO1, MCM10, CENPF and CENPE, that are normally not expressed in healthy breast tissue but become frequently activated in breast cancers." (PMID 37592220, 2023).
cervical cancer (9 papers, 2013 to 2025). A primary or metastatic malignant neoplasm involving the cervix. "Our data indicates that increased MCM10 protein levels indeed correspond with the highly aggressive HPV variant of cervical cancer." (PMID 39086679, 2023). "In order to understand if MCM10 is associated with the aggressiveness of cervical cancer, we looked into the mRNA expression pattern of MCM10 in three cervical cancer cell lines and one normal cervical cell line." (PMID 39086679, 2023). "Our results show that MCM10 expression levels in cervical cancer cell lines are associated with cancer aggressiveness, demonstrating its clinical significance." (PMID 39086679, 2023). "MCM10, part of the mini-chromosome maintenance complex, is essential for DNA replication and genomic stability, and its aberrant expression is implicated in various cancers, including cervical cancer." (PMID 39795915, 2024). "In order to understand if MCM10 expression is associated with the aggressiveness of cervical cancer, we looked into the mRNA expression pattern of MCM10 in four cervical cell lines HeLa (HPV18), SiHa (HPV16), C33A (non-HPV) and HCK1T (normal cervical epithelium)." (PMID 39086679, 2023). "Our analysis revealed that the transcriptional level of MCM10 expression is significantly higher in cervical cancer (CESC) than in any other cancer types like BRCA, COAD, LUAD, OV, UCS and THCA." (PMID 39086679, 2023). "Staining showed that the MCM10 protein was localized to the nucleus of the cervical cancer cell lines." (PMID 39086679, 2023). "Based on our experimental and in silico findings, we propose MCM10 levels are significantly upregulated in aggressive forms of cervical cancer as evident from the overexpression signal obtained from cervical cancer cell lines." (PMID 39086679, 2023). "MCM10 can play a key role in the detection of early stages of cervical cancer and screening younger women for MCM10 expression levels can aid in preventing cervical cancer from progressing to its advanced stages." (PMID 39086679, 2023). "Using the GEPIA database, we investigated MCM10 expression of the top six cancers that affect women, including cervical cancer." (PMID 39086679, 2023). "The expression of the DNA replication protein MCM10, as seen in more aggressive cervical cancers such as Hela cells, results in the initiation of additional DNA replication origins." (PMID 39086679, 2023). "We highlight the clinical significance of MCM10 expression through experimental validation in cervical cancer cell lines." (PMID 39086679, 2023). "Many previous studies have reported that MCM10 expression is high in a number of cancers such as lung cancer, cervical cancer, urothelial carcinoma, gastric cancer, esophageal cancer and BC 27-31." (PMID 35813483, 2022). "Significantly higher expression of MCM10 has been observed in patients with different types of cancers such as lung cancer, cervical cancer, urothelial carcinoma, gastric cancer, esophageal cancer and prostate cancer." (PMID 35813483, 2022). "And an over-expression of the minichromosome maintenance 10 replication initiation factor (MCM10) has been suggested to be involved in the progression of cervical cancer." (PMID 27341628, 2016). "Here we report the expression of MCM subunits, in particular MCM10, which was found to be significantly upregulated in aggressive forms of cervical cancer, and we speculate that MCM10 levels could be an important marker for the aggressiveness of cancer." (PMID 39086679, 2023). "MCM10 is thus a promising candidate for early detection of cervical cancer." (PMID 39086679, 2023). "Hence, we propose MCM10 as an important marker to assess cervical cancer progression." (PMID 39086679, 2023).
cervical cancer (continued). "However, the role of MCM10 in the development of cervical cancer, its link to aggressiveness is unknown." (PMID 39086679, 2023). "The logFC values of the MCM2, MCM10, POLA1, and TONSL in cervical cancer versus normal groups are 2.3, 3.37, 1.76, and 0.587, respectively." (PMID 37746664, 2023). "This module's four proteins, MCM2, MCM10, POLA1, and TONSL, are cervical cancer driver genes based on the DriverDBv3 report." (PMID 37746664, 2023). "Meanwhile, the overexpression of MCM4, MCM5, MCM6, MCM10 and RECQL4 mRNA has been reported as a poor prognostic indicator in cervical cancer." (PMID 29463213, 2018). "Our data indicates the role of MCM4, MCM5, MCM6, MCM10 and RECQL4 in the progression of cervical cancer." (PMID 23874974, 2013). "MCM10 and MCM2 overexpression have been reported in urothelial and cervical cancers." (PMID 30042885, 2018). "MCM4, 5 and 6 also show differential expression in different types of lesion, while MCM2 and MCM10 are over expressed in cervical cancer irrespective of clinico-pathological parameters." (PMID 23874974, 2013).